SAP30BP (SAP30 binding protein)
Description:
Plays a role in transcriptional repression by promoting histone deacetylase activity, leading to deacetylation of histone H3. Acts as a regulator of pre-mRNA splicing by facilitating assembly of the cyclin-L-CDK11 cyclin-dependent protein kinase complex, thereby promoting phosphorylation of SF3B1. May be involved in the regulation of beta-2-microglobulin genes (By similarity). (Microbial infection) Involved in transcriptional repression of HHV-1 genes TK and gC.
Synonyms: HCNGP; HTRG; HTRP
Tractability: PROTAC: UniProt records ubiquitination sites on it; ubiquitination databases record sites on it; its protein half-life has been measured.
Gene: Protein-coding gene on chromosome 17 (75,667,230 to 75,708,062, forward strand). Ensembl gene ENSG00000161526.
Subcellular location: Nucleus; Nucleus speckle
Subcellular location (Human Protein Atlas): Nucleoplasm
Pathways (Reactome):
Gene expression (Transcription): NoRC negatively regulates rRNA expression
Gene Ontology:
Molecular function: cyclin-dependent protein serine/threonine kinase regulator activity; protein binding
Biological process: regulation of mRNA splicing, via spliceosome; response to virus; regulation of DNA-templated transcription
Cellular component: nuclear speck; nucleoplasm; nucleus
Genetic constraint (gnomAD): Loss-of-function variants: 18 observed, 24.04 expected, observed/expected ratio (o/e) 0.75, 90% interval 0.52 to 1.11. The upper end of that interval is the gene's LOEUF score, 1.11, which puts it in group 4 of 6, group 1 being the genes least tolerant of losing a copy. Missense variants: 193 observed, 263.7 expected, observed/expected ratio (o/e) 0.73, 90% interval 0.65 to 0.82. Synonymous variants: 119 observed, 101.14 expected, observed/expected ratio (o/e) 1.18, 90% interval 1.01 to 1.37.
Homologues: Orthologues: chimpanzee SAP30BP (100% identical), macaque SAP30BP (99% identical), pig SAP30BP (98% identical), dog SAP30BP (97% identical), guinea pig SAP30BP (97% identical), rabbit SAP30BP (97% identical), rat Sap30bp (97% identical), mouse Sap30bp (96% identical), tropical clawed frog sap30bp (80% identical), zebrafish sap30bp (67% identical), Drosophila melanogaster CG2063 (38% identical), Caenorhabditis elegans eelo-1 (22% identical).
Diseases named in the same sentence as SAP30BP in open-access papers:
SAP30BP is named in the same sentence as 6 diseases in open-access papers, as found by Europe PMC text mining. Sharing a sentence is not in itself a finding about the gene and the disease. The quoted sentences say what the papers report.
rotator cuff tears (4 papers, 2019 to 2023). "Studies have identified significant evidence of an association of rs820218 in the SAP30-binding protein (SAP30BP) gene with rotator cuff tears in the American population." (PMID 36833294, 2023). "In summary, our study has shown that the genetic polymorphism of SAP30BP contributes to the risk of rotator cuff tears in Chinese Han populations." (PMID 32843068, 2020). "Our study showed that a genetic polymorphism located within the region of the SAP30BP gene was significantly associated with the disease status of rotator cuff tears." (PMID 32843068, 2020). "The aim of this study was to evaluate the potential association of the SAP30BP gene with the susceptibility to rotator cuff tears in a Han Chinese population." (PMID 32843068, 2020). "Our study has shown that the genetic polymorphism of SAP30BP contributes to the risk of rotator cuff tears in Chinese Han people." (PMID 32843068, 2020). "Therefore, the objective of this research was to investigate the relationship of the single-nucleotide rs820218 polymorphism of the SAP30-binding protein (SAP30BP) gene with rotator cuff tears in the Amazonian population." (PMID 36833294, 2023). "Among them, a recently published study documented the results of the GWASs on rotator cuff tears conducted to date and identified significant evidence of an association of rs820218 in the SAP30-binding protein (SAP30BP) gene with rotator cuff tears in the American population." (PMID 32843068, 2020). "Therefore, in the present study, we conducted a case-control association study to evaluate the relationship between the SAP30BP gene and rotator cuff tears in a Han Chinese population." (PMID 32843068, 2020). "Currently, no information is available on the Han Chinese population regarding the SAP30BP gene and rotator cuff tears." (PMID 32843068, 2020). "Sequencing-based studies on genetic regions and the functional significance of SAP30BP are needed in the future to identify the genetic architecture of rotator cuff tears." (PMID 32843068, 2020). "The rs820218 variant of the SAP30BP gene does not contribute to the risk of rotator cuff tears in the present sample of the Amazonian population." (PMID 36833294, 2023). "Moreover, two SNPs, residing in SAP30BP on chromosome 17 and SASH1 on chromosome 6, implicated in the cellular process of apoptosis, were significantly associated with rotator cuff tears." (PMID 32303186, 2020). "Previous studies have suggested that the SAP30BP gene may play an essential role in the development of rotator cuff tears." (PMID 32843068, 2020). "We found that the frequency of the A allele in the control group was four times as high as that in the case group (AA homozygotes), while an association of the genetic variant rs820218 of the SAP30BP gene with rotator cuff tears was not established (p = 0, 28 and 0.20)." (PMID 36833294, 2023). "Hence, it is reasonable to suppose that the SAP30BP gene may be involved in the occurrence and development of rotator cuff tears by inducing apoptosis in tendons." (PMID 32843068, 2020).
breast carcinoma (2 papers, 2021). "For example six SEREX antigens identified in serum from breast cancer patients (RAD50, PARD3, SPP1, SAP30BP, NY-BR-62, and NY-CO-58) could identify breast cancer patients from healthy donors with 70% sensitivity and 91% specificity." (PMID 33976232, 2021).
Obesity (1 paper, 2013). Accumulation of substantial excess body fat. "Eight genes (BCAT1, BMP2 K, CSRNP2, MYNN, NCKAP5L, SAP30BP, SLC35B4, and SP1) were isolated as candidates for obesity." (PMID 24455749, 2013).
rheumatoid arthritis (1 paper, 2020). A chronic, systemic autoimmune disorder characterized by inflammation in the synovial membranes and articular surfaces. "Increased levels of SAP30BP have been demonstrated to be present in synovial cells in rheumatoid arthritis (RA) patients, which indicates that SAP30BP may promote the death of related cells or some cytokines in patients with RA, preventing the prompt activation of certain immune pathways." (PMID 32843068, 2020).
cancer (1 paper, 2020). A tumor composed of atypical neoplastic, often pleomorphic cells that invade other tissues. "From our top 10 specific TFs, only 3 are differently expressed in this cancer type (PLXNB2, NRG1, SAP30BP)." (PMID 33057419, 2020).
SAP30BP also shares sentences with these, for which no sentence is quoted: oligodendroglioma (1 paper).